VCAM1 (vascular cell adhesion molecule 1)
Diseases named in the same sentence as VCAM1 in open-access papers (continued):
Sharing a sentence is not in itself a finding about the gene and the disease.
tumor (continued). "99mTc-cAbVCAM1-5 is therefore a suitable tool to evaluate the role of VCAM-1 as a marker of tumor aggressiveness of TNBC." (PMID 31340603, 2019). "The tumor cells were gated as mCherry+, then the expression of VCAM-1 and apoptosis rate were analyzed." (PMID 30894509, 2019). "TNF-α can also stimulate the transcription of genes encoding endothelial cell adhesion molecules, including E selectin, ICAM-1, VCAM-1, and Madcam1, which are closely related to tumor metastasis and angiogenesis." (PMID 31600735, 2019). "In a mouse model of melanoma, increased IL-12 promotes NKp46+CD49b−RORγt+ILC3 expansion leading to upregulation of VCAM1 to facilitate leukocyte infiltration and the mediation of tumor suppression." (PMID 32117199, 2019). "Previous reports showed that the VCAM-1 expression in tumor cells has been considered as a potential therapeutic target in immune evasion." (PMID 29301329, 2018). "And by doing these, it increases intercellular adhesion molecule-1 (ICAM-1) and vascular cell adhesion molecule-1 (VCAM-1) in endothelial cells of tumor." (PMID 29849819, 2018). "In this section, we will highlight the specific roles of VCAM-1 on tumor angiogenesis and metastasis." (PMID 29614819, 2018). "In this study, we radiolabeled VCAM-1scFv with 99mTc using succinimidyl 6-hydrazinium nicotinate hydrochloride (SHNH) to detect levels of VCAM-1 in several tumor models in vivo." (PMID 29853809, 2018). "VCAM-1 is believed to be responsible for tumor proliferation and metastasis, and its levels correlate with prognosis." (PMID 29853809, 2018). "This was associated with a decrease in invasion-associated genes (e.g., Fibronectin, VCAM1, Thrombospondin, MMP1) and an increase in CDH1/E-cadherin, previously associated with decreased tumor aggression." (PMID 29735912, 2018). "The immunofluorescence intensities of the tumor tissues, which were extracted from different tumor-bearing mice of the 4 h biodistribution groups, further validated the different VCAM-1 expression levels of six tumor models." (PMID 29853809, 2018). "Considering the aberrant expression of VCAM-1 in tumor biology, the development of noninvasive molecular imaging for VCAM-1 is crucial for better tumor diagnosis, prognosis, and therapy planning." (PMID 29853809, 2018). "Baseline angioprotein-1 and hepatocyte growth factor showed a direct correlation with tumor volume whereas changes in vascular cell adhesion molecule 1 showed significant correlations with 18F-fluorothymidine (FLT) positron emission tomography (PET)." (PMID 29398577, 2018). "The in vitro transfection of microRNA-181a-5p, a tumor suppressor, downregulates VCAM-1 expression and impedes IL-17-induced proliferation and the migration of H226 and H460 non-small cell lung cancer cells." (PMID 29614819, 2018). "The findings suggested that expression of VCAM-1 in tumors promoted T-cell migration away from tumors, resulting in decreased accumulation of T cells in the tumor microenvironment." (PMID 29301329, 2018). "We identified different expression levels of VCAM-1 with SPECT planar imaging of corresponding tumor lesions, which potentially provides a qualitative and semiquantitative method for noninvasive evaluation of VCAM-1 expression in vivo." (PMID 29853809, 2018). "To gain insights into the pathological cross-talk between tumor and stromal cells, we next explored the expression of VCAM-1 in PDAC cells and its dynamic relationship with macrophages recruitment." (PMID 29670110, 2018). "Ligands for the endothelial cell adhesion molecules ICAM-1, VCAM-1, E-selectin and N-cadherin were found to be expressed on tumor cells and to mediate tumor-endothelial cell interaction." (PMID 30204757, 2018). "Compared with si-NC cells, VCAM-1 downregulation greatly attenuated tumor cell proliferation in PANC-1 and Capan-2 cells, as determined by a CCK-8 assay." (PMID 29670110, 2018).
tumor (continued). "Among the factors and pathways that regulate the progression of CSCs to bone metastases there are also VCAM1, tumor-induced OC miRNAs and Jagged1." (PMID 29461491, 2018). "Vcam1 and C1qb were undetectable in both tumor epithelia and PBMC but readily detected in whole tumors, suggesting expression in other cell lineages/biological contexts such as endothelium/ coagulation." (PMID 28632792, 2017). "Vascular endothelial growth factor receptors (VEGFR), integrin, matrix metalloproteinase receptor, and vascular cell adhesion molecule 1 (VCAM-1) are the targets for impairment of angiogenesis in tumor tissue." (PMID 29464123, 2017). "VCAM-1 (vascular cell adhesion molecule 1) promotes tumor angiogenesis; and its mRNA expression was positively related to the lymph node metastasis." (PMID 28077802, 2017). "Early up‐regulation of VCAM1 was found in vessels related to micrometastases, with expression increasing with tumor growth." (PMID 27279574, 2017). "The expression of VCAM1 on the cell surface has been shown to increase the survival of tumor cells by decreasing the number of infiltrating lymphocytes." (PMID 29215599, 2017). "Our data also confirmed CD163 was associated with VCAM1 (r=0.42) and CLECA7 (r=0.71) which had been used to identify tumor associated macrophages recently." (PMID 29152078, 2017). "The intercellular adhesion molecule 1 (ICAM-1), the vascular cell adhesion molecule 1 (VCAM-1), E-selectin and galectin-3 have been reported to be involved in the interaction of tumor and endothelial cells." (PMID 29100413, 2017). "Integrin α4β1 (VLA-4) is also expressed by tumour cells and allows their adhesion through its interaction with vascular cell adhesion molecule-1 (VCAM-1) expressed by stromal cells in the bone marrow." (PMID 27782035, 2016). "On the other hand, 99% (82/83) of the PTC patients exhibited L-Selectin expression and the IRS-9 was observed as the median score and VCAM-1 expression was positive in 84% (70/83) of the tumours with median score as IRS-2." (PMID 26881177, 2016). "VCAM-1 mRNA levels were similarly upregulated with tumor cell infusion for all diets except SeGP65 at 48 h post tumor cell infusion." (PMID 26706037, 2016). "On the other hand, a significant inverse correlation of VCAM-1 expression was seen with the presence of multifocality of tumours (χ2 = 4.040, r = −0.221, P = 0.045)." (PMID 26881177, 2016). "While the increased expression of VCAM1 promotes tumor invasion and metastasis, high levels of VTN and/or FN1 in circulation have been reported to promote tumor formation and metastasis." (PMID 26930275, 2016). "The expression of ICAM-1 and VCAM-1 adhesion molecules was up-regulated on tumor endothelial cells only when anti-CD40 mAb treatment was combined with sunitinib." (PMID 27385210, 2016). "Five of these genes, CXCL12, MMP2, MMP11, VCAM1, and MME, which have previously been associated with tumor progression, angiogenesis, and metastasis, clearly discriminated between primary BC and BCBM." (PMID 27340107, 2016). "For instance, tumor-associated macrophages can interact with metastasizing breast cancer cells in the lung via VCAM-1 and promote tumor cell survival." (PMID 27608835, 2016). "In a recent article, tumor-derived SPARC was found to trigger endothelial paracellular permeability in primary human umbilical vein endothelial cell (HUVEC) monolayers via VCAM1 and p38 signaling, thus disrupting endothelial monolayer integrity." (PMID 27581191, 2016). "There was a significant interaction between dietary treatment and tumor cell infusion on VCAM-1 mRNA expression." (PMID 26706037, 2016). "The mesothelial VCAM1 is possibly responsible for tumour cell adhesion by interacting with integrin α1β1 and α4β7 on tumour cells." (PMID 27074785, 2016). "For instance, breast cancer cell expression of VCAM-1 has been shown to bind with integrin α4β1 to promote the recruitment of osteoclast precursors, leading to tumour cell reactivation." (PMID 27782035, 2016).
tumor (continued). "Metastatic tumour cell attachment to ECs has been shown to induce the endothelial activation markers VCAM‐1 and VAP‐1." (PMID 25677806, 2015). "Constitutive c-Met expression and enhanced angiogenic properties in SCCOHT-1 cells are also supported by their capacity of to produce and release VEGF and VCAM-1 into the tumor microenvironment which are essential for tumor neo-vascularization." (PMID 26436697, 2015). "We next performed tumor cell binding assays in the presence of neutralizing antibodies against E-selectin, ICAM-1 or VCAM-1 to investigate the role these adhesion molecules in tumor cell binding." (PMID 26509633, 2015). "Accordingly, endothelial VCAM-1 expression was induced by tumor-cell embolus that resulted in increased recruitment of myeloid cells supporting metastasis." (PMID 24592356, 2014). "It is also known that in several types of cancers VCAM-1 is aberrantly expressed on the surface of tumor cells thereby tethering macrophages to tumor cells and generating favorable conditions for tumor angiogenesis, invasion and metastasis." (PMID 25030093, 2014). "Tumor-cell glycan-induced and P-selectin-dependent endothelial activation resulted in enhanced expression of E-selectin and vascular cell adhesion molecule 1 (VCAM-1) and promoted lung colonization and metastasis." (PMID 24592356, 2014). "The authors found that overexpression of VCAM-1 by cancer cells led to decreased apoptosis of tumor cells and a significant decrease in the number of tumor-infiltrating CD8+ T cells expressing VCAM-1." (PMID 25030093, 2014). "TF-triggered tumor cell-clot formation induces vascular cell adhesion molecule-1 (VCAM-1) expression and the recruitment of myeloid cells, and promotes tumor invasion and metastasis." (PMID 25084809, 2014). "Adding IDO-blockade led to upregulation of VCAM-1 on vascular endothelium within the tumor microenvironment, and further adding radiation in the presence of IDO-blockade led to widespread deposition of complement." (PMID 25054064, 2014). "Continuous section slides were made and stained for ICAM-1, VCAM-1 and tumor infiltrating CIK cells respectively." (PMID 23799045, 2013). "This can be understood in terms of the fact that the cytokine-cascade induced after endothelial stimulation increases the expression of adhesion molecules, such as VCAM-1, to which tumor cells can adhere." (PMID 23301091, 2013). "Recent studies from our laboratory indicate that integrin α4β1, a receptor for vascular cell adhesion molecule 1 (VCAM-1) and CS-l fibronectin, selectively promotes the homing of myeloid cells to the tumor microenvironment." (PMID 22938502, 2012). "Macrophages in the metastatic niche provide survival signals for VCAM-1-expressing tumor cells through direct intercellular interactions." (PMID 22699312, 2012). "Radiation has been shown to upregulate endothelial cell adhesion molecules, such as ICAM-1, VCAM-1 and P-selectin, especially in microvascular or tumor endothelial cells." (PMID 20877628, 2010). "Homing to the tumor is probably due to interaction between activated T cells and antigen-independent inflammatory ligands such as Vcam-1." (PMID 19127288, 2009). "Here we analyzed changes in the content of VCAM-1 in endothelial cells under experimental treatments with TNF or TFS's that led to an increase in tumor cell adhesion." (PMID 19930605, 2009). "Histological studies of the expression of adhesion molecules, as such as VCAM-1 in primary vascular tumoral tissue, can serve to compare endothelial models with the behavior of cells in vivo." (PMID 19930605, 2009). "The VLA-4/VCAM-1 interaction is critical for recruitment of NK cells into lung, liver, and tumor sites." (PMID 18534032, 2008). "A pathophysiologicalrelevant fact worthwhile to be mentioned is that endothelial cells coexpress SDF-1α and VCAM-1,thus mediating tumor-cell/endothelial cell attachment." (PMID 19266088, 2008).
tumor (continued). "VCAM-1 was positively correlated with age and negatively with degree of tumour differentiation and haemoglobin concentration." (PMID 9667659, 1998). "Given the promising results treating smaller, vascularised tumours (VCAM-1 & lymphoid targeting therapies) compared to the relative difficulty with melanin targeted melanoma treatments, i.v. administered mAb targeted therapy appears to be profoundly influenced by the tumour environment." (PMID 40591218, 2025). "Macrophages accumulate around the tumor cells through the binding of VLA-4 to homologous VCAM-1." (PMID 40927361, 2025). "For example, tumor‐associated ECs frequently display reduced expression of vascular adhesion molecules (such as ICAM‐1 and VCAM‐1), which are required for the homing and trafficking of immune cells and act as a barrier to prevent immune cells from entering the tumor interior." (PMID 41346571, 2025). "Nevertheless, our findings suggest that, for intracranial glioma, VLA-4Hi lymphocytes may be able to encounter VCAM-1 and accumulate in tumor." (PMID 40244705, 2025). "Third, studies should investigate whether the exercise-related increase in VCAM-1 reflects enhanced immune mobilization and contributes to a more favorable tumor microenvironment." (PMID 41583457, 2025). "ICAM-1 and VCAM-1 are key adhesion molecules that mediate leukocyte adhesion and migration across the endothelium, thereby regulating the immune responses, inflammation, and tumour progression." (PMID 41294859, 2025). "These oncogenic features of SOX17 and SOX18 are supported by their significant co-expression with endothelial and inflammatory mediators such as VCAM1 and STAT3, both of which are known to drive tumor-associated angiogenesis, immune evasion, and metastatic potential." (PMID 41373817, 2025). "Histological assessment of TPCS at days 1, 4, 8, and 11 revealed that TME characteristics were maintained throughout the 11-day culture period: dense tumor tissue was highlighted via H&E stain, alongside an αSMA+ stroma, and a VCAM-1+ endothelium, which developed throughout the culture period." (PMID 40377490, 2025). "Interestingly, the overexpression of TGF‐β has been shown to suppress the expression of VCAM‐1 in tumour endothelium, enabling tumour cells to evade immunosurveillance." (PMID 40038875, 2025). "In tumor, high levels of VEGF, VCAM-1 and ICAM-1 were significantly associated with low-medium SCS." (PMID 40652770, 2025). "Some studies have shown that VEGF may suppress VCAM-1 expression to facilitate tumor immune evasion." (PMID 41583457, 2025). "VCAM1’s localization at the tumor border, in particular, may reflect its role in mediating adhesion between tumor and endothelial cells—a key step in metastatic dissemination." (PMID 41373817, 2025). "Currently, the complex relationship between VCAM-1 expression and immune cell infiltration and its effects on the patient overall survival (OS) and tumor infiltration patterns remain unknown." (PMID 40927361, 2025). "These leukocytes appear to promote the growth and survival of VCAM-positive tumours and metastases, specifically by conveying anti-apoptotic signals via surface VCAM-1 clustering, subsequent recruitment of phosphorylated ezrin, and downstream PI3-kinase/Akt activation." (PMID 40095109, 2025). "Moreover, VCAM-1, along with other CAMs, has been implicated to have a functional role not only in leukocyte trafficking during IBD but also in tumour cell invasion and metastasis in CRC." (PMID 40095109, 2025). "Tumor vessel ICAM-1/VCAM-1 expression decreases by 70%, reducing T cell adhesion efficiency by 85%." (PMID 41415289, 2025). "Consequently, upon disruption of the LFA-1/ICAM-1 and VLA-4/VCAM-1 axes, NK cells lose their intravascular localization, compromising surveillance of metastasizing tumor cells." (PMID 41145419, 2025). "Traditionally, VCAM-1 upregulation has been thought to promote tumor angiogenesis and metastasis." (PMID 41583457, 2025).
tumor (continued). "Notably, SOX18 appears to function as a central node within a transcriptional network involving MEF2C, p-STAT3, and VCAM1—particularly in the tumor vasculature and invasive front—underscoring its relevance to tumor microenvironment remodeling." (PMID 41373817, 2025). "However, under gemcitabine treatment, PAK4KO significantly upregulated both ICAM-1 and VCAM-1 compared with WT tumours, suggesting an activation of these molecules following the gemcitabine treatment." (PMID 41294859, 2025). "Therefore, VCAM-1/α4β1 interactions are remarkably versatile, being capable of leukocyte-endothelial, tumour-leukocyte, and tumour-endothelial attachment." (PMID 40095109, 2025). "Furthermore, the reduction in the expression of key angiogenic genes (i.e., Pecam1, Vcam1, Flt1, and Kdr) indicates that rifaximin effectively inhibits the angiogenic switch, which is critical for tumor growth and metastasis." (PMID 40724957, 2025). "Similar to its adhesive function in immune cell trafficking, VCAM-1 expressed on the surface of tumour cells tethers leukocytes, endothelial cells, and other innate cells that express α4 integrins, enhancing adhesion-based processes such as cell invasion and metastasis." (PMID 40095109, 2025). "This inverse relationship may reflect compartmentalized inflammation, with increased local shedding of VCAM-1 into ascites due to a more inflamed tumor microenvironment." (PMID 40652770, 2025). "Disruption of lymphatic junctions and increased permeability via tumor-induced lymphatic VCAM-1 expression may represent a new target to block lymphatic invasion and metastasis." (PMID 41511312, 2025). "Sustained levels of VEGF correlated with low levels of VCAM-1 in the endothelium that may consist in a mechanism of defense from tumor cells promoting their immune evasion by precluding immune infiltration." (PMID 40071851, 2025). "Additionally, the movement of T-cells from blood vessels to the tumor site is hindered by the downregulation of extravasation mediators, including vascular cell adhesion molecule-1 (VCAM-1) and intercellular adhesion molecule-1 (ICAM-1)." (PMID 41019052, 2025). "Finally, VCAM-1 expression on tumor cells contributes mostly to cancer progression via the recruitment of macrophages and subsequent changes in tumor vasculature favoring cancer cell dissemination." (PMID 40071851, 2025). "Furthermore, IL-6 increases the expression of adhesion molecules, such as ICAM-1, VCAM-1 and E-selectin on endothelial cells, as well as L-selectin on lymphocytes, which results in increased transmigration of leukocytes into the tumor area." (PMID 41009634, 2025). "VCAM-1 serves a functional role across several distinct intercellular interactions and signalling pathways—not only as a surface receptor on endothelial cells, but also ectopically in tumour cells and as a soluble form in serum." (PMID 40095109, 2025). "Additionally, PEO and its components inhibit adhesion molecules, such as intracellular adhesion molecule 1 (ICAM-1) and vascular cell adhesion molecule 1 (VCAM-1), which are involved in tumor progression, suggesting their potential role in cancer suppression." (PMID 40219102, 2025). "Next, we investigated whether depleting macrophages could synergize with anti-VCAM1 antibody to augment anti-tumor efficacy of iNKT cells." (PMID 38332012, 2024). "Nevertheless, VCAM-1 is important for immune cell trafficking, and the mechanism responsible for promoting tumor survival remains unknown." (PMID 38786066, 2024). "Therefore, the premise for tumor metastasis through ICAM-1/VCAM-1–mediated myeloid cell–CTC clustering is such that the myeloid cell–CTC interaction should be permissive." (PMID 38786066, 2024). "Moreover, in the tumor area, the RT upregulates the adhesion molecules (including ICAM-1 and VCAM-1), which are also expressed in blood vessels that predispose to immune cell infiltration of the tumor microenvironment." (PMID 38203748, 2024).